TMBIM6 (transmembrane BAX inhibitor motif containing 6)
Diseases named in the same sentence as TMBIM6 in open-access papers (continued):
Sharing a sentence is not in itself a finding about the gene and the disease.
COVID-19 (2 papers, 2020 to 2021). A disease caused by infection with severe acute respiratory syndrome coronavirus 2. "This study identified TMBIM6 as a target protein associated with the pathogenesis of SARS-CoV-2, which might provide a novel therapeutic approach for COVID-19 in the future." (PMID 33744846, 2021). "Chemical compound screening and drug design targeting TMBIM6 might provide a novel clinical approach for the treatment of COVID-19 in the future." (PMID 33744846, 2021). "For example, TMBIM6 expression was not significantly different in autopsied lung tissues from deceased COVID-19 patients at the transcriptional level." (PMID 33744846, 2021).
diabetic nephropathy (2 papers, 2022 to 2024). "Thus, the upregulation of miR-27a-3p is positively associated with diabetic nephropathy via miR-27a-3p-prohibitin/TMBIM6 signaling axis." (PMID 36297381, 2022). "Further, it was observed that miR-27-3p inhibits the expression of prohibitin and transmembrane BAX inhibitor motif containing 6 (TMBIM6), which play a role in the progression of diabetic nephropathy." (PMID 36297381, 2022).
dyslipidemia (2 papers, 2016 to 2020). "Our study suggests that loss-of-function of TMBIM6 might contribute to the development of metabolic syndrome and further understanding of its role will contribute to the development of novel strategies to prevent or treat this serious condition." (PMID 32394396, 2020).
heart failure (2 papers, 2022 to 2023). Inability of the heart to pump blood at an adequate rate to meet tissue metabolic requirements. "Thus, stabilization of TMBIM6 expression, inhibition of PS2 activation and preservation of mitochondrial function are promising therapeutic strategies to reduce reperfusion-caused cardiomyocyte dysfunction and heart failure." (PMID 36923943, 2023). "However, TMBIM6 plays an irreplaceable role in the myocardial protection mechanism and is an unimportant regulatory pathway for GN to treat diabetic cardiomyopathy or heart failure." (PMID 35401934, 2022).
Hyperinsulinemia (2 papers, 2020 to 2024). An increased concentration of insulin in the blood. "We therefore conclude that lack of TMBIM6 does not affect insulin sensitivity but leads to hyperinsulinemia, which serves to explain the weight gain." (PMID 32394396, 2020).
laryngeal carcinoma (2 papers, 2023). Carcinoma that arises from the laryngeal epithelium. "For instance, as a ‘writer’ of m6A modified way, RBM15 could facilitate proliferation and migration of laryngeal carcinoma cells by modifying TMBIM6 in laryngeal carcinoma." (PMID 36734243, 2023).
liver cancer (2 papers, 2010 to 2019). An epithelial or non-epithelial malignant neoplasm that arises from the liver. "Immunohistochemistry analyses confirmed that the expression levels of PKCι, Sp1, and TMBIM6 were correlated with one another in samples from human breast, prostate, and liver cancer patients." (PMID 31336725, 2019). "Additionally, the immunohistochemistry data demonstrated the expression pattern of the PKCι, Sp1, and TMBIM6 is well matched in breast, prostate, and liver cancer clinical tissue samples." (PMID 31336725, 2019).
lung adenocarcinoma (2 papers, 2008 to 2020). A carcinoma that arises from the lung and is characterized by the presence of malignant glandular epithelial cells. "We found that patients with high TMBIM6 expression had poor survival in breast invasive carcinoma (BRCA), cervical squamous cell carcinoma and endocervical adenocarcinoma (CESC), sarcoma (SARC), and lung adenocarcinoma (LUAD)." (PMID 32782388, 2020).
Sepsis (2 papers, 2024 to 2025). Sepsis is defined as life-threatening organ dysfunction caused by a dysregulated host response to infection. "TMBIM6 can exert cardioprotective effects against LPS-induced sepsis by interacting with mitochondrial Ca2+ uptake, inhibiting/blocking overexpression of the VDAC1, and preventing its oligomerization." (PMID 39664568, 2024). "Meanwhile, TMBIM6 overexpression has been shown to enhance the interaction with VDAC1, thereby protecting myocardial mitochondria and cardiac function against sepsis." (PMID 40694561, 2025).
atherosclerosis (1 paper, 2024). A disease characterized by the build-up of fatty material and calcium deposition in the arterial wall resulting in partial or complete occlusion of the arterial lumen. "This study utilized animal and cellular gene modification techniques, along with metabolomic analysis, to further validate the role of TMBIM6-NDUFS4-mediated mitophagy in the pathological mechanisms of atherosclerosis (AS)." (PMID 39494338, 2024). "This novel insight suggests that TMBIM6-NDUFS4 may serve as a key therapeutic target for atherosclerosis." (PMID 39494338, 2024).
autism (1 paper, 2016). Persistent deficits in social interaction and communication and interaction as well as a markedly restricted repertoire of activity and interest as well as repetitive patterns of behavior. "GABPA was recently found to bind human-specific binding sites and regulate gene expression of at least four genes (ALDOA, HSPA8, TP73, and TMBIM6) that have been associated with cognitive diseases such as autism, AZ, PD and other brain disorders." (PMID 27014338, 2016).
bladder cancer (1 paper, 2025). "This discovery not only expands our understanding of TMBIM6’s oncogenic functions but also provides new insights into the molecular mechanisms underlying ferroptosis resistance in bladder cancer." (PMID 40610429, 2025). "Collectively, our findings suggest that si-TMBIM6 impedes bladder cancer cell proliferation and migration by inducing cellular ferroptosis." (PMID 40610429, 2025). "To delve deeper into the role of TMBIM6 in ferroptosis within bladder cancer cells, we conducted additional experiments." (PMID 40610429, 2025). "Both TCF3 and TMBIM6 emerge as promising biomarkers and therapeutic targets for bladder cancer intervention." (PMID 40610429, 2025). "In summary, our research demonstrates that TCF3 promotes the development of bladder cancer by inducing Ca2+-dependent ferroptosis resistance through its interaction with TMBIM6." (PMID 40610429, 2025). "In this study, we systematically investigated the expression profile of TMBIM6 in bladder cancer and further elucidated its regulatory role in Ca2+-dependent ferroptosis pathways." (PMID 40610429, 2025). "Our investigation revealed a parallel between the effects of TMBIM6 knockdown and Erastin treatment on ferroptosis induction in bladder cancer cells." (PMID 40610429, 2025). "Our findings revealed elevated TMBIM6 expression in bladder cancer cell lines compared to the SV-HUC-1 group, with 5637 cells exhibiting the highest levels and T24 cells showing the lowest." (PMID 40610429, 2025). "Despite these significant advances, the functional significance and molecular mechanisms of TMBIM6 in bladder cancer pathogenesis remain unexplored." (PMID 40610429, 2025). "Our findings demonstrate that TCF3 directly interacts with TMBIM6 and transcriptionally upregulates its expression, thereby mediating Ca2+-dependent ferroptosis resistance and facilitating bladder cancer progression." (PMID 40610429, 2025). "Our findings demonstrate that TCF3 facilitates bladder cancer progression through the enhancement of TMBIM6-Ca2+-mediated ferroptosis resistance." (PMID 40610429, 2025). "TMBIM6 and ferroptosis-related proteins were up-regulated in bladder cancer tissues, but CaM was downregulated." (PMID 40610429, 2025). "Functional experiments demonstrated that siRNA-mediated knockdown of TMBIM6 effectively suppressed bladder cancer cell proliferation through the induction of ferroptosis." (PMID 40610429, 2025). "Subsequently, TMBIM6 was either overexpressed or inhibited in T24 and 5637 cells to validate its effects on bladder cancer cells." (PMID 40610429, 2025). "Building upon these previous findings, our study has made a novel observation in bladder cancer: we identified significantly elevated expression levels of TMBIM6 and ferroptosis-related proteins (GPX4, SLC7A11, and FTH1) in clinical bladder cancer specimens." (PMID 40610429, 2025). "In conclusion, our study unveils that TCF3 is significantly overexpressed in bladder cancer, suggesting its role in accelerating bladder cancer advancement by interacting with TMBIM6." (PMID 40610429, 2025). "TCF3 and TMBIM6 emerge as promising biomarkers and therapeutic targets for bladder cancer." (PMID 40610429, 2025). "TMBIM6 may promote tumor development by inducing ferroptosis resistance in bladder cancer cells, which is an innovative point of our study." (PMID 40610429, 2025). "This study aimed to explore the roles and mechanisms of TMBIM6 in bladder cancer." (PMID 40610429, 2025). "This led us to speculate that si-TMBIM6 may influence the proliferation of bladder cancer cells by promoting ferroptosis." (PMID 40610429, 2025). "Next, we examined the expression of TMBIM6 in SV-HUC-1 and bladder cancer cell lines (T24, EJ, 5637, UM-UC-3, BIU-87)." (PMID 40610429, 2025). "Initially, we evaluated the expression of TMBIM6 in SV-HUC-1 and various bladder cancer cell lines (T24, EJ, 5637, UM-UC-3, BIU-87)." (PMID 40610429, 2025).
bladder cancer (continued). "In this study, we observed elevated expression levels of TMBIM6 and ferroptosis-related proteins (GPX4, SLC7A11, and FTH1) in bladder cancer tissues, while CAM expression was significantly downregulated." (PMID 40610429, 2025). "TMBIM6, ferroptosis-related proteins (GPX4, SLC7A11, and FTH1), and calmodulin (CaM) expressions in bladder cancer and paracancerous tissues were obtained by immunohistochemistry." (PMID 40610429, 2025). "TMBIM6 overexpression enhanced proliferation, invasion, migration, GSH/GPX4 levels, and ferroptosis resistance while suppressing MDA, Fe2+, and lipid ROS in bladder cancer cells, effects reversed by Erastin." (PMID 40610429, 2025). "While previous research has established that TMBIM6 modulates intracellular Ca2+ dynamics to regulate ER stress-induced cell death in various cellular models, including HeLa, HT1080, and MEFs, its potential role in ferroptosis regulation, particularly in bladder cancer, remains unexplored." (PMID 40610429, 2025).
Brain atrophy (1 paper, 2019). Partial or complete wasting (loss) of brain tissue that was once present. "Furthermore, administration of Ad-TMBIM6 significantly reduced brain atrophy versus vehicle." (PMID 31636086, 2019).
cervix (1 paper, 2016). "We have identified and validated CHCHD1, SRSF9 and TMBIM6 as reference genes for studying hypoxia-related gene expression in fresh-frozen clinical samples from squamous cell carcinoma of the uterine cervix by RT-qPCR." (PMID 27244197, 2016).
esophageal cancer (1 paper, 2024). A primary or metastatic malignant neoplasm involving the esophagus. "Through analysis of the TCGA database, we initially observed a significant association between high TMBIM6 expression and poor prognosis in esophageal cancer patients." (PMID 38706912, 2024).
Hepatic steatosis (1 paper, 2020). Steatosis is a term used to denote lipid accumulation within hepatocytes. "TMBIM6 knockout mice, however, featured a higher glucose-stimulated insulin secretion in vivo as assessed by the hyperglycemic clamp test and hepatic steatosis." (PMID 32394396, 2020).
ischemia (1 paper, 2022). A hypoperfusion of the BLOOD through an organ or tissue caused by a PATHOLOGIC CONSTRICTION or obstruction of its BLOOD VESSELS, or an absence of BLOOD CIRCULATION. "It has been found that TMBIM6/BI1 overexpression can inhibit the expression of myocardial XO, eliminate the excessive accumulation of ROS, block drp1-mediated mitochondrial fission, and protect myocardial injury and coronary microvascular injury caused by ischemia." (PMID 35401934, 2022).
oral squamous cell carcinoma (1 paper, 2026). "Significance: Palmitic acid promotes metastasis via a stromal CEBPG-IRE1α/TMBIM6 axis, uncovering a metabolic vulnerability that offers novel therapeutic targets to inhibit oral squamous cell carcinoma." (PMID 42227941, 2026).
prostate adenocarcinoma (1 paper, 2025). "As far as we know, we are the first to find and describe the DHRS4-AS1/hsa-miR-222-3p/TMBIM6 axis as a possible prediction biomarker for prostate adenocarcinoma." (PMID 41516091, 2025). "We investigated the possible connection between immune cell infiltration and TMBIM6 expression in prostate adenocarcinoma." (PMID 41516091, 2025). "Together, these findings imply that this ceRNA axis TMBIM6/miR-222-3p/DHRS4-AS1 might serve as a new prognostic biomarker in prostate adenocarcinoma." (PMID 41516091, 2025). "Through demonstration of a link of TMBIM6 expression with epithelial infiltrations, this work suggests TMBIM6 fosters EMT processes, thereby underpinning enhanced invasiveness and higher risks of metastatic spread in prostate adenocarcinoma." (PMID 41516091, 2025).
salivary gland cancer (1 paper, 2023). A primary or metastatic malignant neoplasm that affects the major or minor salivary glands. "The results showed that TMBIM6 mutations were increased in several cancer types, particularly in breast and salivary gland cancer with alteration frequencies." (PMID 37057283, 2023).
xerostomia (1 paper, 2020). Dryness of the mouth resulting from reduced salivary secretion. "In SS patients both with xerostomia (sicca) and without xerostomia (non-sicca), TMED10, PDIA4, CANX, APP, and TMBIM6 expression was lower than in HS." (PMID 33066537, 2020).
cancer (26 papers, 2007 to 2025). A tumor composed of atypical neoplastic, often pleomorphic cells that invade other tissues. "To analyze TMBIM6 mutations and copy number alternations (CNAs) in various cancer types, we used the cBioPortal database to investigate mutations in various parts of TMBIM6, particularly in V185D / I." (PMID 37057283, 2023). "Although many pieces of evidence supported the involvement of TMBIM6 in the development of various cancers, the molecular mechanism underlying the role of TMBIM6 in cancer progression has been less studied." (PMID 32782388, 2020). "Functioning as a Ca2+ channel-like protein, TMBIM6 has been demonstrated to exhibit upregulated expression profiles across multiple cancer types, particularly in breast cancer, glioblastoma, and non-small cell lung cancer." (PMID 40610429, 2025). "Co-expression and immune infiltration studies revealed further correlations with STEAP2, PIK3B, and epithelial cells, suggestive of TMBIM6 impacting cancer progression in multiple manners." (PMID 41516091, 2025). "Further elucidation of the molecular mechanisms governing TMBIM6's functions holds promise for the development of novel therapeutic strategies for cancer treatment." (PMID 38766879, 2024). "Transmembrane Bax Inhibitor Motif-containing 6 (TMBIM6) has been reported to regulate cell death pathways and is overexpressed in several types of cancers." (PMID 37057283, 2023). "Several studies have indicated that miRNAs can promote the migration and metastasis of cancer cells 53-55, thus, we also investigated miRNAs expression in TMBIM6 knockdown cells." (PMID 37057283, 2023). "Through analysis of the GEPIA2 database, we found that the TMBIM6 transcription level was even higher in most cancers." (PMID 33744846, 2021). "To investigate the oncogenic role of TMBIM6 in cancer progression, we first analyzed TMBIM6 mRNA expression profiling datasets of multiple tumor samples from the NCBI/GEO." (PMID 32782388, 2020). "Based on the interaction between TMBIM6 and mTORC2 and its biological effects, the TMBIM6–mTORC2 axis is an actual signaling mechanism that can be target for cancer therapy." (PMID 32782388, 2020). "To evaluate the signaling protein molecule, which regulates the cancer progression in WT and TMBIM6 KO HT1080 cells, we performed protein phospho-kinase profiling analysis." (PMID 32782388, 2020). "On the other hand, TMBIM6-overexpressing HT1080 cells showed upregulation of genes related to cancer progression and metastasis." (PMID 32782388, 2020). "TMBIM6, a member of the transmembrane BI-1 motif-containing family of proteins, is overexpressed in many cancer types." (PMID 32782388, 2020). "Next, we compared the expression levels of TMBIM6 in same cancer tissues using tissue microarrays and obtained the similar results." (PMID 32782388, 2020). "Increasing evidences supporting the involvement of TMBIM6 in physiological processes and in various cancer developments led us to study the transcriptional regulation of TMBIM6, which has not been studied much." (PMID 31336725, 2019). "Altogether, this study suggests the involvement of Sp1 in basal transcription and PKC in the enhanced expression of TMBIM6 in cancer." (PMID 31336725, 2019). "In H-score analysis, we found significantly increased expression levels of Sp1, PKCι, and TMBIM6 proteins in cancer tissues from normal tissues." (PMID 31336725, 2019). "In this study, we offer the first report of the basal transcriptional regulation of the human TMBIM6 gene and the possible mechanisms related to its enhanced transcription in cancer." (PMID 31336725, 2019). "Results showed higher viable cells in P9-TMBIM6-HA transfected cells compared to P9-(mSp1d, mSp1p)-TMBIM6-HA cells, indicating the Sp1-dependent TMBIM6 expression role in the cancer cell protection against stress." (PMID 31336725, 2019).